CDK4 (cyclin dependent kinase 4)
Diseases named in the same sentence as CDK4 in open-access papers (continued):
Sharing a sentence is not in itself a finding about the gene and the disease.
glioma (continued). "Cyclin D1 and CDK4 are key proteins in the regulation of the cell cycle and are overexpressed in human gliomas." (PMID 34485271, 2021). "Oncogenic drivers including PIK3C2B, EGFR, and CDK4 are amplified in gliomas with low TOX expression." (PMID 32762688, 2020). "GISTIC 2.0 analysis identified several significant regions of amplification harboring multiple oncogenes in gliomas with a high-risk score, including 1q32.1 (PIK3C2B), 4q12 (PDGFRA), 7p11·2 (EGFR), and 12q14·1(CDK4)." (PMID 32023222, 2020). "Taken together, these results indicate that MPT0B291 inhibited cell proliferation by inducing G1 cell cycle arrest and down-regulating G1/S regulators Cdk2 and Cdk4 in glioma cells." (PMID 33162824, 2020). "While determining the mechanisms that miR‐5188 promotes glioma progression, we confirmed that overexpression of miR‐5188 up‐regulated protein levels of CDK4, CCND1, c‐JUN, N‐cadherin and vimentin." (PMID 32902145, 2020). "Protein mass spectrometry was used to identify the tumor suppressor genes up‐regulated by AQB.The effects of HOTAIR ‐ EZH2 inhibitor AQB and CDK4/6 inhibitor Palbociclib on glioma cells lines were examined in vitro and in vivo experiments." (PMID 32508030, 2020). "The combination of AQB and CDK4/6 inhibitor palbociclib is more effective in inhibiting the growth of glioma than in the single drug, both in vivo and in vitro." (PMID 32508030, 2020). "NVP-HSP990 disrupted cell-cycle control mechanisms by decreased CDK2 and CDK4 levels and increased glioma tumor-initiating cell apoptosis levels." (PMID 33390934, 2020). "The combination of AQB and CDK4/6 inhibitor palbociclib has been found to have significant antitumor effects, which is likely to become a new strategy for glioma treatment." (PMID 32508030, 2020). "In the glioma pathway (hsa05214), included in CDK4 (Cyclin Dependent Kinase 4), PRKCG (Protein Kinase C Gamma) and EGFR." (PMID 32696617, 2020). "In this way, to attain the potential molecular mechanisms by which CUL7 promotes glioma development, we detected the expression changes of some key mediators of cell proliferation and apoptosis, including p21, p27, cyclin D1, CDK4, cyclin E1 and CDK2." (PMID 32252802, 2020). "Due to heterogeneity of glioma, we additionally investigated the patient prognosis with CDK4/CDK6 and TUBA1C expression in every grade of glioma in CGGA datasets." (PMID 32860670, 2020). "Our analysis of a subset of astrocytoma cases within The Cancer Genome Atlas (TCGA) glioma dataset showed similar results with mutual exclusivity between CDK4 and CDKN2A alterations in all except one case." (PMID 32640746, 2020). "Out of the well-predicted genes, CDK4, MMP7, MYCBP, and TMEM59 in gliomas and LCP1 in RCC have been implicated in multiple cancer types." (PMID 32194984, 2020). "In LGG, the ceRNAs shared by MTAP and CDKN2A contained many genes highly associated with gliomas and other cancers, such as IDH1 and CDK4/6." (PMID 31719831, 2019). "The largest community in LGG contained 798 nodes, including some glioma-associated genes like IDH1 and CDK4/6, in which most ceRNA pairs were driven by copy number deletion." (PMID 31719831, 2019). "Consistently, IHC staing of CCNB1, CCND1, and CDK4 of the 21 glioma specimens confirmed that the protein expression levels of these cell cycle gene are correlated with PRMT2 in different grades of gliomas." (PMID 30382083, 2018). "Experiments from the current study showed that LOC441204 enhances the growth ability of glioma cell lines and stimulates proliferation through protection and activation of β-catenin/p21/cdk4 components." (PMID 28717243, 2017). "In conclusion, this is the first report to demonstrate involvement of the lncRNA LOC441204 in glioma cell proliferation via a mechanism involving the β-catenin/p21/cdk4 cascade." (PMID 28717243, 2017). "Briefly, LOC441204 bound to β-catenin preventing its degradation, resulting in downstream p21 repression and cdk4 activation to enhance glioma cell proliferation." (PMID 28717243, 2017).
glioma (continued). "To further demonstrate the regulatory role of cyclin D1 in the glia-fate induction of glioma cells, we introduced a functional pharmacologic inhibitor of CDK4 and 6 which bind to cyclin D1 to form a complex required for G1-S cell cycle phase progression." (PMID 27515956, 2016). "In this assay, we found that CDK4 was highly expressed in high-grade glioma tissues compared with low-grade glioma tissues; however, p27Kip1 and p21Waf1/Cip1 showed opposite results." (PMID 26856755, 2016). "To measure the expression of p27Kip1, p21Waf1/Cip1 and CDK4 in glioma tissues, we performed the IHC staining assay." (PMID 26856755, 2016). "Based on these data, we believe that Sch B arrests the cell cycle in G0/G1-phase to suppress the proliferation of glioma cells by reducing the expression of cyclin D1 and CDK4." (PMID 25685066, 2015). "We previously reported that EZH2 was upregulated in glioma and promoted glioma cells growth through inhibition of CDK4/6-pRb-E2F1 signal pathway." (PMID 25831237, 2015). "Amplification and over expression of CDK4 has been detected in sarcoma and glioma, but in carcinoma the picture seems to be unclear." (PMID 22932448, 2012). "The CDK4 is amplified and over expressed in a number of human tumors including the gliomas, sarcomas, breast tumors and colorectal carcinomas." (PMID 22932448, 2012). "Our immuno precipitation experimentspresent evidence that, treatment of glioma cells with hUCBSC leads to thearrest of cell-cycle progression through inactivation of both cyclin D1/Cdk4 and cyclin D1/Cdk 6 complexes." (PMID 21455311, 2011). "Some pathways associated with higher grade gliomas are upregulation of PDGFRA (platelet derived growth factor receptor α), CDK4 (cyclin dependent kinase 4) and down-regulation of retinoblastoma (RB1)." (PMID 21884623, 2011). "D-cyclins, established Myc target genes, and Cdk4 are also commonly amplified and/or overexpressed in gliomas." (PMID 19214224, 2009). "At variance with CDK2, only one major single phosphorylated form of CDK4 is observed in a variety of cell types, including dog and human thyrocytes, human fibroblasts, T98G glioma cells, Rat2 fibroblasts..." (PMID 17092340, 2006). "In addition, Xi’an Bao and colleagues have uncovered that sevoflurane (Sev) inhibits glioma progression through the regulatory network of HMMR-AS1/miR-7/CDK4." (PMID 40806330, 2025). "Finally, we visualized the close association between CDCA3 and common glioma cell cycle checkpoint markers, including CDK6, CDK4, CDK2, CDK1, CDKN3, and CDKN2C, using circos plots." (PMID 38728485, 2024). "Genetic aberrations associated with worse prognoses, such as PDGFRA amplification, CDKN2A or CDKN2B deletion, and CDK4 amplification, may lead to further glioma subdivision." (PMID 38672625, 2024). "CDK4/6 inhibition suppresses tumour growth and enhances the effect of temozolomide in glioma cells." (PMID 38073225, 2023). "In glioma, the activity of CDK4/6 inhibitors depends on the wild type of Rb." (PMID 35785151, 2022). "Cyclin D1, a regulatory subunit of CDK4/6 in turn, is increasingly expressed in glioma cells." (PMID 34687436, 2022). "It has been reported that CDK4 knockdown impedes the colony formation and cell proliferation of glioma, and that PBK and SLC2A3 could be a potential prognostic factor and therapeutic target for GBM treatment." (PMID 36358948, 2022). "CDK4/6 dysfunction is common in high-grade glioma and promotes phosphorylation of RB1." (PMID 34687436, 2022).
glioma (continued). "High expression of CDK4 in glioma tissues was predicted via GEPIA." (PMID 34719318, 2021). "In glioma cells, CDK4 is overexpressed which led to glioma cell proliferation and TMZ resistance." (PMID 33918704, 2021). "In terms of prognostic analysis, consistent with our previous results, high expression of CDK4, HMGB2, and WEE1 could lead to poor prognosis of glioma; however, gliomas with high expression of SMC3 and GADD45G were linked to longer survival." (PMID 34123852, 2021). "Taken together, these results demonstrated that HDGF-mediated c-Jun regulation could promote glioma cell proliferation by inducing CCND1/CDK4/CDK6." (PMID 34959221, 2021). "Here we hypothesized that Sev might target the HMMR-AS1/miR-7/CDK4 axis to regulate glioma progression." (PMID 34719318, 2021). "Interestingly, PDFGR signaling promotes tumorigenesis in concert with CDK4 in a murine glioma model." (PMID 34008925, 2021). "Sevoflurane regulates the HMMR-AS1/miR-7/CDK4 axis in glioma cells." (PMID 34719318, 2021). "Besides, NE promotes the proliferation of glioma cells by regulating the expression of cyclin D1/CDK4/6 and Bcl‐2/Bcl‐XL, while curcumin can reverse these effects to alleviate tumour progression induced by adverse psychological stress." (PMID 34169637, 2021). "Sev represses glioma cell progression by regulating HMMR-AS1/miR-7/CDK4 axis." (PMID 34719318, 2021). "Taken together, these results demonstrated that c-Jun enhanced upon HDGF overexpression could promote glioma cell proliferation by inducing the activation of the CCND1/CDK4/CDK6 signaling axis." (PMID 34959221, 2021). "CDK4 was targeted via miR-7, and highly expressed in glioma." (PMID 34719318, 2021). "GISTIC 2.0 analysis revealed that in gliomas with high-risk scores, the amplification mainly occurred in chromosomal regions 1q32.1, 3q26.33, 4q12, 7p11.2, and 12q14.1, where several key oncogenes (PDGFRA, EGFR, MDM2, SOX2, and CDK4) were located." (PMID 35116021, 2021). "Additionally, recent studies have shown that overexpression of the CDK4 gene was closely related to poor prognosis of patients with glioma." (PMID 34123852, 2021). "Additionally, five DDRGs (CDK4、HMGB2、WEE1、SMC3 and GADD45G) were selected to construct a DDRGs signature for glioma, stratifying patients into low- and high-risk groups." (PMID 34123852, 2021). "It was hypothesized that Sev could target the HMMR-AS1/miR-7/CDK4 axis to inhibit glioma progression." (PMID 34719318, 2021). "More importantly, CDK4 was reported to be regulated via Sev in glioma." (PMID 34719318, 2021). "For example, those infiltrating gliomas with FGFR-TACC fusions may present with other oncogenic alterations including CDKN2A loss, CDK4 amplification, MDM2 amplification and/or TERT promoter mutations." (PMID 32493417, 2020). "Furthermore, amplification peaks of oncogenes (PIK3C2B, PDGFRA, EGFR, CDK4), and deletion peaks of tumor suppressor genes (TUSC1, CDKN2A, CDKN2B, PTEN, FAS, BNIP3) were detected in the gliomas with a high risk score." (PMID 32023222, 2020). "Some studies have shown that co-deletion of CDKN2A and MTAP could be used as markers for glioma stratification, and the deletion of CDKN2A was associated with the expression of CDK4/6 in various tumors." (PMID 31719831, 2019). "For example, miR-124 could inhibit the growth of glioblastoma by downregulating SOS1, radio-sensitizing human glioma cells by targeting CDK4, and suppressing the migration and invasion of glioma cells via Capn4 and ROCK1." (PMID 31052326, 2019). "By inhibiting CDK4 and CDK6, p16 impedes cell cycle progression from G1 to S phase and acts as a tumor suppressor that has been implicated in the prevention of cancers, notably gliomas." (PMID 29489901, 2018). "We found that LPS induced the expression of CDK4/6 and cyclin E in glioma CD133+ CSCs, which might promote increased proliferation of these cells." (PMID 28881826, 2017).
glioma (continued). "CDK4 is a key factor in promoting the initiation and development of tumors, and amplified and over expressed in a number of human tumors including the gliomas, sarcomas, breast tumors and colorectal carcinomas." (PMID 24160369, 2013). "Similarly, we also found the oncogenic role of CDK4 in glioma by promoting colony formation." (PMID 34719318, 2021). "Previous studies reported CDK4 could facilitate glioma cell proliferation and restrain apoptosis." (PMID 34719318, 2021). "Moreover, CDK4 contributes to glioma cell growth, which is mediated via miR-129." (PMID 34719318, 2021). "This study found that CDK4 might promote glioma cell invasion." (PMID 34719318, 2021). "Moreover, CDK4 was predicted to be centralized in the glioma pathway (hsa05214)." (PMID 32696617, 2020). "Therefore, combinatorial treatments compensating also for loss of function mutations (e.g. CDK4/6 inhibition for homozygous CDKN2A/B deletion) and targeted elimination of glioma stem cells before clonal evolution occur, could increase treatment success in these tumor entities." (PMID 41331048, 2025). "In glioma and ovarian cancers, NAP1L1, via its interaction with HDGF, activated c-Jun, an oncogenic transcription factor, to induce CCND1/CDK4/CDK6 expression resulting in cellular proliferation and chemoresistance to cisplatin." (PMID 40176914, 2025). "This study illuminates Sev’s potential mechanism of action on glioma cells by influencing cell growth, invasion, and the formation of colonies through the interaction of lncRNA HMMR-AS1 with miR-7 and CDK4." (PMID 40806330, 2025). "There is a negative correlation between the expression level of miR-124 and that of CDK4 and CDK6 in glioma samples." (PMID 40134003, 2025). "A related study found that hepatogenic growth factor acts in conjunction with c-Jun to induce CCND1/CDK4/CDK6 expression and promote the proliferation of gliomas." (PMID 40138292, 2025). "The results showed that patients in different groups defined by age, FGFR2, IDH1, CDK4, CDK6, KIT, and CDKN2A had significantly different OS in all glioma grades." (PMID 37273702, 2023). "Meanwhile, the amplification of EGFR and CDK4, and the deletion of PTEN and CDKNA2A/B were observed in the gliomas with high PVT1 expression." (PMID 37202742, 2023). "Alterations in CDK4/6, CIC, FGFR2/3/4, FUBP1, KIT, MET, NF1, PEG3, RB1, and NTRK2 were additional factors correlated with the survival of different subtypes of gliomas." (PMID 36998447, 2023). "Based on their prognostic relevance in glioma samples, the seven variables age, FGFR2, IDH1, CDK4, CDK6, KIT, and CDKN2A were selected for the construction of the WHO5 risk signature." (PMID 37273702, 2023). "Naringenin supplementation for 1 month can reduce lipid peroxidation and decrease the expression of PKC, NF-κB, cyclin D1(CCND1) and cyclin-dependent kinase 4 (CDK4), thereby inhibiting the proliferation of glioma cells in mouse models." (PMID 38130720, 2023). "Age, FGFR2, IDH1, CDK4, CDK6, KIT, and CDKN2A were considered vital indicators related to the prognosis and OS time of glioma." (PMID 37273702, 2023). "The p38-MAPK pathway is activated in rat glioma cells treated with chrysin, resulting in the accumulation of p21 (WAF1/CIP1) protein, decreased activities of CDK2 and CDK4, and cell cycle arrest in G1 phase." (PMID 38130720, 2023). "Of the 17 gliomas in our molecular high-grade group, 82% had either CDKN2A inactivation (n = 13) or CDK4 amplification (n = 1)." (PMID 35945463, 2022). "Known prominent events include TMPRSS2-ERG in PCa, EGFR, CDK4, and MDM2 in glioma, and CCND1 in BrCa." (PMID 34891161, 2021).
glioma (continued). "The results showed that there was a positive correlation between NUP37 and most known biomarkers of glioma such as ATRX, EGFR MGMT, CDK4, and so on." (PMID 34264013, 2021). "In glioma samples with high LYN expression, oncogenic driver genes such as EGFR (7p11.2) and CDK4 (12q14.1) were frequently amplified, while tumor suppressor gene PTEN (10q23.31) and CDKN2A (9p21.3) were frequently deleted." (PMID 35186945, 2021). "Cyclin D1 and CDK4 are downstream proteins of AKT which control cell cycle regulation and promote glioma cells proliferation." (PMID 34485271, 2021). "There were multiple, cancer type–specific hot spots of junctions located near known oncogenes such as KIT, PDGFRA, EGFR, CDK4, MDM2 (glioma), TMPRSS2, ERG (PCa), FGFR1, and CCDN1 (BrCa)." (PMID 34891161, 2021). "Analysis of TCGA datasets in glioma patients confirmed significant positive correlation of ITGA6 expression with CDK1, CDK4, PCNA, and FOXM1 transcript levels." (PMID 34205341, 2021). "Western blot analysis and IHC showed that cyclin D1, cyclin D2, CDK4, CDK6, Ki-67, Bcl-2 and Bax were involved in the NRXN3-induced inhibitory effect on glioma growth." (PMID 34035217, 2021). "The combination therapy of CDK4/CDK6 and mTOR inhibitors resulted in the synergistic growth arrest of diffuse bridge glioma cells." (PMID 32508030, 2020). "Exosomes derived from the peripheral blood samples of human glioma patients are reported to carry GBM-specific gDNA of ERBB2, CDK4, AKT3, MDM2, and RB1 genes." (PMID 33137926, 2020). "In our study, mRNA level of Cdk2, Cdk4 and Cdk6 down-regulated in MPT0B291-treated glioma cells indicating that HDAC6 inhibitor transcriptionally regulates those cyclin-dependent kinases." (PMID 33162824, 2020). "In this study, 47.6% of glioma patients were detected ctDNA including 1p/19q, MDM2, ERBB2, IDH1, CDKN2A, CDK4, PDGFRA, CCNE1, MET." (PMID 32973641, 2020). "In “secondary glioma pathway”, gains of PDGFA (1 in LGG and 2 in HGG), PDGFRA (2 in LGG and 2 in HGG) and CDK4 (1 in LGG and 2 in HGG) and RB1 (2 in HGG), and losses of RB1 (1 in LGG and 2 in HGG) are also identified." (PMID 23451178, 2013). "The changes of CDK4/6 and p21 mediated by ZEB2 knockdown in the U251 glioma cell line suggest potential avenues to target these proteins in tumors." (PMID 22761708, 2012). "Our data argue that Cdk4 activity is a key tumor-specific rate-limiting output of EGFR and PI3K signaling in glioma as well." (PMID 19214224, 2009). "All three high grade lines had highly complex genomic profiles and harboured amplifications and deletions at several known cancer genes dysregulated in paediatric glioma, including CCND1, MYC, CDK4, PIK3CA, CDKN2A/B, and RB1." (PMID 19365568, 2009). "The increased expression of tumor-suppressors is common in many cancer types, including cyclin dependent kinase inhibitor p16Ink4a in glioma and HPV-induced cancers, CDK4/6 inhibitor p18Ink4c in cervical cancer and glioblastoma, and CDK2 and PCNA inhibitor p21 in many types of cancer." (PMID 40568073, 2025). "Although both CDK4 amplifications and loss of CDKN2A/B have been largely described in gliomas, they do not seem to cooccur." (PMID 39211518, 2024). "Additionally, FDA-approved drug targets among these genes revealed 30 such targets, with CDK4 and FCGR1A identified as glioma-specific and ADORA3 as brain-specific, according to the Human Protein Atlas." (PMID 39457550, 2024). "Finally, we combined the results of the XGB model and univariate Cox regression analysis to identify age, FGFR2, IDH1, CDK4, CDK6, KIT, and CDKN2A as crucial predictors of prognosis and OS time for glioma patients." (PMID 37273702, 2023). "CDK4 and CDK6, which regulate the cell cycle, played an important role in glioma pathogenesis." (PMID 37273702, 2023).